HMGB1 (high mobility group box 1)
Diseases named in the same sentence as HMGB1 in open-access papers (continued):
Sharing a sentence is not in itself a finding about the gene and the disease.
Autoimmunity (continued). "There in increasing evidence that HMGB1 could represent a biomarker for disease activity, might act as pro-inflammatory mediator as well as inducer of autoimmunity in GPA." (PMID 36275673, 2022). "It has been reported that HMGB1 is involved in various inflammatory responses and autoimmunity." (PMID 35250993, 2022). "The present data support the possibility that HMGB1 could be a viable therapeutic target to prevent the initiation, progression and recurrence of autoimmunity in the setting of type 1 diabetes." (PMID 32072192, 2020). "Furthermore, patients with active disease present with higher levels of serum/plasma HMGB1 than those with inactive disease, highlighting its importance as a mediator of autoimmunity." (PMID 31379812, 2019). "In autoimmunity, there are many reports demonstrating that neutralizing antibodies or drugs that directly target HMGB1 can reduce inflammation and stimulate the development of Tregs, ameliorating symptoms of diseases like type 1 diabetes, autoimmune thyroiditis, and graft-vs.-host disease." (PMID 31379812, 2019). "Even though HMGB1 was first described as a nuclear protein, today we know that it is also one of the major cytokine-like mediators of inflammation and its pathological discontents, such as autoimmunity and cancer." (PMID 31379812, 2019). "RAGE and its ligand high mobility group box 1 (HMGB1) play key roles in autoimmunity and cancer." (PMID 24705787, 2014). "Like HMGB1 and autoantibodies, HSPs may contribute to the development of autoimmunity not only as endogenous adjuvants but also as chaperones that physically deliver autoantigens to APCs." (PMID 23772226, 2013). "High-mobility group box 1 (HMGB1), a DAMP with pleiotropic functions, is involved in various intracellular (e.g., chromatin remodeling, transcription, autophagy) and extracellular (inflammation, autoimmunity) processes, which has been associated with both protumor and antitumor functions." (PMID 35003065, 2021). "Therefore, we next examined whether neutralising HMGB1 would prevent the recurrence of autoimmunity and prolong islet isograft survival in NOD mice." (PMID 32072192, 2020). "It has been speculated that non-cleared apoptotic cells can assume characteristics of “secondary necrotic cell death,” leading to HMGB1 release to the extracellular milieu and driving autoimmunity further, but whether this effect relies on HMGB1 alone remains to be clarified." (PMID 31379812, 2019). "High-mobility group box 1, originally described as a nuclear protein that binds to and modifies DNA, is now regarded as a vital mediator of inflammation by acting as a cytokine in clinical conditions such as autoimmunity, cardiovascular disease and cancer 40–42." (PMID 23480850, 2013). "Necrotic cell debris contains several DAMPs (DNA, histones, adenosine triphosphate (ATP), high mobility group box 1 (HMGB1), and actin, among others) that interact with PRRs, triggering excessive inflammation and potentially leading to autoimmunity." (PMID 40943586, 2025). "Future studies should explore HMGB1’s interactions with TLR2/CD36 in B cells, its role in human autoimmune disorders, and whether its cytoskeletal functions intersect with metabolic pathways like oxidative phosphorylation, which was impaired in cKO B cells." (PMID 40985892, 2025). "By bridging transcriptional control and cytoskeletal dynamics, HMGB1 ensures that B cells remain poised for defense without tipping into autoimmunity, a delicate equilibrium essential for immune health." (PMID 40985892, 2025). "Thus, HMGB1 and RAGE are involved in autoimmunity by transmitting intracellular signals and acting as a carrier between the extracellular and intracellular compartments." (PMID 33807604, 2021).
Autoimmunity (continued). "Our previous study has demonstrated that HMGB1 is released from melanocytes under oxidative stress, and then promotes the skin migration of CD8+ T cells and the maturation of dendritic cells, thus contributing to the formation of oxidative stress-induced autoimmunity in vitiligo." (PMID 36569840, 2022). "High-mobility group B1 (HMGB1) is both a DNA binding nuclear factor modulating transcription and a crucial cytokine that mediates the response to both infectious and noninfectious inflammation such as autoimmunity, cancer, trauma, and ischemia reperfusion injury." (PMID 38580917, 2024).
esophageal squamous cell carcinoma (33 papers, 2014 to 2025). Esophageal squamous cell carcinoma (ESCC) is a type of esophageal carcinoma (EC) that can affect any part of the esophagus, but is usually located in the upper or middle third. "High levels of HMGB1 were found in plasma-derived sEVs of esophageal squamous cell carcinoma patients and were associated with radioresistance of tumor cells." (PMID 37998605, 2023). "In esophageal squamous cell carcinoma, the concomitant presence of tumor cells expressing high levels of high-mobility group box 1 (HMGB1) and peritumoral regions with high density of proliferating B cells is an unfavorable prognostic factor." (PMID 38426109, 2024). "In patients with esophageal squamous cell carcinoma, HMGB1 was found to positively correlate with patient survival and was found upregulated in the tumor following preoperative chemoradiotherapy." (PMID 35903697, 2022). "Studies have reported that HMGB1 expression is highly increased in esophageal squamous cell carcinoma (ESCC)." (PMID 34456716, 2021). "For example, CXCL12 induces recruitment of TAMs after forming a complex with HMGB1 under the influence of CXCR4, and esophageal squamous cell carcinoma-derived exosomes (EXOs) promote PD1+ TAM expansion via HMGB1." (PMID 32551121, 2020). "Our findings are consistent with a recent study demonstrating that tumor-derived exosomal HMGB1 promotes the progression of esophageal squamous cell carcinoma through inducing expansion of PD1+ M2-phenotype TAM12." (PMID 32788720, 2020). "β-catenin/TCF4 complex was found to transactivate HMGB1, thus promoting DNA damage repair in esophageal squamous cell carcinoma upon exposure to IR." (PMID 29567990, 2018). "HMGB1 is confirmed to be responsible for cisplatin resistance in esophageal squamous cell carcinoma (ESCC)." (PMID 28969092, 2017). "Recent studies have shown that about 38% of patients with esophageal squamous cell carcinoma (ESCC) had tumor antigen-specific T cell responses as well as elevated serum HMGB1." (PMID 24434638, 2014). "The high-mobility group box 1 (HMGB1) released by cancer cells is known to attract B cells to the tumor in the esophageal squamous cell carcinoma (ESCC), where B cells undergo rapid multiplication and activate pro-angiogenic phenotypes, promoting the growth of both ECs and tumors." (PMID 37666809, 2023). "Similarly, we found the esophageal squamous cell cancer patients with high expression of HMGB1 showed late TNM stage and short overall survival and progression-free survival in this study, and these were also similar to those of public database TCGA analysis." (PMID 36260180, 2022). "In esophageal squamous cell carcinoma, levels of HMGB1 within the tumor microenvironment were significantly upregulated upon preoperative chemoradiotherapy and patients with a high HMGB1 levels showed a better overall survival compared to those with weak HMGB1 expression." (PMID 26483791, 2015). "Here, we aimed to clarify the effects of HMGB1 on radioresistance in esophageal squamous cell carcinoma (ESCC) cell lines and patient survival." (PMID 35812184, 2022). "Additionally, HMGB1 promotes beclin 1 (BECN1)-dependent autophagy, which subsequently promotes radioresistance in oral squamous or esophageal squamous cell carcinoma (ESCC)." (PMID 41164196, 2025). "Interestingly, chromatin immunoprecipitation assays demonstrated the transactivation of HMGB1 mediated by a β-catenin/TCF4 complex, thus promoting DDR in esophageal squamous cell carcinoma (ESCC) consequent to exposure to ionizing radiation." (PMID 40001953, 2025). "High mobility group box 1 (HMGB1) and indoleamino-2, 3-dioxygenase (IDO) participate in the occurrence and development of esophageal squamous cell carcinoma (ESCC), regulate the tumor immune microenvironment, and are closely related to tumor growth and metastasis." (PMID 39314628, 2024).
esophageal squamous cell carcinoma (continued). "The aim of this study is to determine co-expression patterns of High-mobility group box 1 protein (HMGB1) and receptor for advanced glycation end products (RAGE) in ESCC (esophageal squamous cell carcinoma) conditions and their prognostic role in cancer progression." (PMID 35829833, 2022). "High-mobility group box transcription factor 1 (HMGB1) containing exosomes can successfully trigger the clonal expansion of programmed cell death protein 1 positive (PD1+) TAMs, and finally facilitate esophageal squamous cell carcinoma (ESCC) development." (PMID 34722637, 2021). "Furthermore, the interaction between HMGB1 and RAGE has been shown to be important in neuronal cell apoptosis, and the RAGE axis is also involved in the apoptosis of a number of different cell types, including pancreatic β cells, esophageal squamous cell carcinoma and neuronal cells." (PMID 25187821, 2014).
Hypertension (31 papers, 2012 to 2025). The presence of chronic increased pressure in the systemic arterial system. "There is a possibility that age, gender, and the presence of underlying hypertension could differentially affect the level of serum HMGB1." (PMID 33461910, 2022). "Thus, targeting PDGFR-β-mediated secretion of HMGB1 in VSMCs might be a promising therapeutic strategy for vascular complications associated with hypertension." (PMID 35294955, 2022). "Thus, targeting the MS-PDGFR-β-HMGB1 axis in VSMCs might be a promising therapeutic strategy for vascular complications associated with hypertension." (PMID 35294955, 2022). "Reportedly, HMGB1 is known as a multifunctional protein which induces vascular remodeling in hypertension via phenotypic transformation of VSMCs from contractile to synthetic type." (PMID 35294955, 2022). "In support of this concept, they designed another study to determine the involvement of HMGB1 signaling in Ang II-induced hypertension in the para ventricular nucleus (PVN)." (PMID 34489714, 2021). "Consistent with the elevated HMGB1 levels in hypertension patients, the plasma level of miR-181b-5p was decreased concomitant with an increase in Ang II levels and IMT.These phenomena were attenuated in hypertensive patients following ARB treatment." (PMID 31011475, 2019). "Because high mobility group box-1 (HMGB1) protein has been reported to be involved in several pathogenic processes including VSMC proliferation and migration, Li and co-workers examined the role of HMGB1 in VSMC phenotypic transformation in hypertension." (PMID 31011489, 2019). "The present study was designed to determine the role of HMGB1 in VSMC phenotypic transformation in hypertension." (PMID 31011475, 2019). "Given that the TLR4 blockade reduces MAP, it can be postulated that TLR4 plays role in hypertension, possibly via HMGB1." (PMID 25879545, 2015). "A study of neuroinflammation in the etiology of stress hypertension found that the HMGB1/RAGE axis mediates stress-induced impairment of mitochondrial autophagic flux and immunophenotypic switching of microglia, leading to neuroinflammatory responses such as NFκB activation and PIC release." (PMID 38740617, 2025). "The relationship between HMGB-1 levels and MACE persisted even after adjusting for traditional cardiovascular risk factors such as age, BMI, smoking habits, hypertension, blood lipids, glycemic control and renal function, confirming HMGB-1 as an independent risk factor." (PMID 36244983, 2022). "Based on these reports, it is reasonable to speculate that HMGB1 plays a role in the mediation of Ang II- induced VSMCs phenotypic transformation in hypertension." (PMID 31011475, 2019). "Our current results indicate that HMGB1 has the same function in essential hypertension as in PAH." (PMID 31011475, 2019). "Thus, Ang II/ miR-181b-5p/ HMGB1 might form a novel pathway involved in the regulation of vascular remodeling in hypertension." (PMID 31011475, 2019). "Therefore, one possible mechanism by which TLR4 is activated in hypertension could be via upregulation of HMGB1." (PMID 25879545, 2015). "The necrotic cells secrete injury-associated molecular signatures i.e., heat shock protein 60 or HSP 60 and high-mobility group box 1 (HMGB1) protein, in amplified amounts, in case of cardiac stress, hypertension, metabolic syndrome and ischemic injury." (PMID 40255399, 2025). "TLR4 is one of the crucial receptors of HMGB1; the persistent activation of TLR4 induces the damage of kidney, cardiovascular, and CNS tissue in hypertension." (PMID 34970076, 2021). "The interaction between the inflammatory cytokine protein, HMGB1, and TLR4, resulted in the up-regulation of NF-kB which in turn resulted in hypertension in Neuro-2a cells of mice treated with Ang II." (PMID 34489714, 2021).
Hypertension (continued). "Immunohistochemical analysis further revealed that TGF-beta and NLRP3 inflammasome activation [high-mobility group box 1 (HMGB1), IL-1beta, and NLRP3] were significantly upregulated in the kidney of rats with Ang II-induced hypertension." (PMID 32117956, 2020). "Nevertheless, the present findings provide strong evidence that TLR4 within the PVN plays a critical role in the pathogenesis of hypertension, at least in part, due to increased binding with its specific DAMP, HMGB1." (PMID 25879545, 2015). "Distributions of RAGE ligands were not different between subjects affected and not affected by hypertension, therefore, hypertensive individuals were not removed from the studied population (log_HMGB1 P=0.786; log_S100A8/9 P=0.927; log_AGEs P= 0.993)." (PMID 30903794, 2019). "In the colon, however, baicalin treatment counteracts hypertension-associated increases in the expression of Tlr2, TNF-α, IL-1β, and IL-23 but not HMGB1 in the SHRs." (PMID 31719823, 2019). "The tissue injury resulted from non-immune mechanisms of hypertension leads to DAMP formation, such as ROS, LPS, and high mobility group box 1 (HMGB1)." (PMID 36035928, 2022).
pancreatitis (31 papers, 2010 to 2025). Inflammation of the pancreas. "The initial insult of pancreatitis results in the production of key ligands for TLR4 such as HMGB1 and heat shock proteins associated with sterile inflammation." (PMID 38585277, 2024). "The activation of NLRP3 inflammasome will deteriorate inflammation of pancreatitis, and esults in production of IL-1β, IL-18, and HMGB1, which are associated with systemic injury." (PMID 33967799, 2021). "Inhibiting HMGB1 using anti-HMGB1 neutralizing antibody attenuated the development of pancreatitis and associated organ dysfunction." (PMID 31560698, 2019). "Increased HMGB1 in the pancreas is associated with pancreatic necrosis and frequently used to demonstrate necrotic cell death in pancreatitis patients and ethanol-induced injury to the pancreas." (PMID 27527870, 2016). "Nevertheless, the exact mechanism by which the level of HMGB1 is related to the development and progression of pancreatitis is not fully understood at present." (PMID 40941648, 2025). "Pancreatitis patients with higher HMGB1 levels have also corresponded to increased disease severity." (PMID 38585277, 2024). "There is evidence that macrophages accumulate in the bladder mucosa of mice treated with CPA, macrophage-derived HMGB1 is involved in chemotherapy-induced peripheral neuropathy and pancreatitis-related pain." (PMID 32707767, 2020). "TMα also dramatically reduces the endogenous HMGB1-dependent inflammatory hyperalgesia following intraplantar LPS, cystitis-related bladder pain, and pancreatitis-related pain." (PMID 33396481, 2020). "High-motility group box protein 1 (HMGB1) is recognized as an important predictor for the persistence and further development of pancreatitis." (PMID 33118404, 2020). "It would also have been useful to measure the serum HMGB1 concentration in dogs with comorbidities other than pancreatitis and to differentiate the general effects of AP/SIRS on the serum HMGB1 concentration, compared with the more specific effects of AP/SIRS." (PMID 31401946, 2019). "Serum HMGB1 and IL-6 significantly increased with L-arginine induction of pancreatitis (95.9 ± 21.7 vs. 18.2 ± 9.7 ng/ml, p < 0.0001; 11.66 ± 2.82 vs. 3.85 ± 0.04 nmol)." (PMID 30733719, 2019). "A previous study suggested that SSM inhibited the activation of c-Jun NH2-terminal kinase, p38, and NF-κB in pancreatitis by inhibiting HMGB-1." (PMID 30647762, 2018). "Pancreatic tissue HMGB1 levels are significantly increased in experimental SAP; HMGB1 promotes the pathogenesis of pancreatitis, and inhibiting HMGB1 therapy ameliorates the pancreatic injury." (PMID 28316860, 2017). "In conclusion, the findings from our study indicate that glycyrrhizin can suppress HMGB1 and improve outcomes of traumatic pancreatitis in rats." (PMID 25541713, 2014). "Therefore, the intervention of HMGB-1 and autophagy appears to be a promising alternative option for the gene therapy of pancreatitis." (PMID 33118404, 2020). "Severity of pancreatitis, HMGB1 expression was examined 12 h after induction of ANP." (PMID 28754974, 2017). "Accordingly, we hypothesize that glycyrrhizin may potentially improve the outcome of traumatic pancreatitis by inhibiting HMGB1." (PMID 25541713, 2014). "As for AP, some known extracellular NLRP3 activators like DNA, adenosine triphosphate (ATP), high mobility group box 1 (HMGB1), and nucleotide binding oligomerization domain 2 (NOD2) are all associated with the inflammation during the development of pancreatitis." (PMID 25214720, 2014). "Finally, caspase-3, a key mediator in mitochondrial events of apoptosis, and high mobility group box-1 (HMGB-1), a protein that have an important role in transcription and activation in pro-inflammatory response, also correlated with the severity of pancreatitis, were investigated." (PMID 35041718, 2022).
pancreatitis (continued). "In this pancreatitis-related pain model, adult monocyte-derived macrophages migrate into the pancreatic tissue during the early stage of tissue damage or inflammation, and secrete HMGB1, which in turn activates RAGE and accelerates CXCL12/CXCR4 signaling, resulting in pancreatic pain." (PMID 34440650, 2021). "We have demonstrated that RAGE mediates the allodynia/hyperalgesia following intraplantar administration of at-HMGB1, but not ds-HMGB1, and that the HMGB1/RAGE pathway plays a crucial role in the neuropathic pain caused by spinal nerve injury and visceral pain accompanying cystitis and pancreatitis." (PMID 33396481, 2020).